SPP1 (secreted phosphoprotein 1)
Diseases named in the same sentence as SPP1 in open-access papers (continued):
Sharing a sentence is not in itself a finding about the gene and the disease.
joint diseases (3 papers, 2012 to 2022). "However it is notable that CILP2, like other high-scoring plasma protein markers such as COMP, TNXB, THBS4, SPP1, COL2A1 to name a few, are associated with connective tissue development (cartilage matrix synthesis in the case of CILP2) and bone and joint disorders." (PMID 22558154, 2012).
keloid (3 papers, 2023). An irregularly shaped, elevated mark on the skin caused by deposits of excessive amounts of collagen during wound healing. "At an individual (control/patient) level, SPP1+MAM+ macrophages were significantly increased in IPF lung, SSC lung, keloid skin, and AKI kidney." (PMID 37706477, 2023).
metastatic colorectal cancer (3 papers, 2022 to 2025). "In metastatic colorectal cancer, cell-to-cell communication between SPP1-expressing TAMs and CAFs has been suggested to be involved in CTL dysfunction, and SPP1-expressing TAMs are characterized by a foamy cell gene signature." (PMID 37190178, 2023).
motor neuron disease (3 papers, 2016 to 2024). "In this study, we aimed to investigate the systemic inflammatory profile and serum Spp1 levels in patients with ALS and SBMA, and to examine the associations of Spp1 levels with clinical variables and other systemic inflammatory markers in motor neuron diseases (MNDs)." (PMID 38775192, 2024). "In this study, we investigated systemic inflammatory profiles, including serum Spp1, in patients with two distinct motor neuron diseases, ALS and SBMA." (PMID 38775192, 2024).
myocardial ischemia (3 papers, 2011 to 2024). A disorder of cardiac function caused by insufficient blood flow to the muscle tissue of the heart. "Remarkably, macrophages co-expressing Spp1 and Trem2 were identified within the infarct zone of the mouse myocardial ischemia-reperfusion model." (PMID 38449872, 2024).
neuroblastoma (3 papers, 2019 to 2024). Neuroblastoma (NB) is the most common solid, extracranial childhood tumor. "The ALKBH5 gene, linked to NB susceptibility, has been reported to inhibit NB progression by reducing YAP expression and activity, and to promote malignant progression by inhibiting SPP1 expression in high‐grade neuroblastoma, where it is often amplified and upregulated." (PMID 38925618, 2024).
neuroendocrine tumors (3 papers, 2019 to 2023). "These include CHGA (also associated with neuroendocrine tumors), CFH, SPP1, and an immunoglobulin-like receptor." (PMID 30678299, 2019).
osteomalacia (3 papers, 2017 to 2025). Disorder caused by an interruption of the mineralization of organic bone matrix leading to bone softening, bone pain, and weakness. "At ten days of age, Spp1−/− mice have extracellular PPi levels even higher than those observed in the Alpl−/− mice, where extracellular PPi excess promotes rickets/osteomalacia." (PMID 28303318, 2017).
peripheral nerve injury (3 papers, 2020 to 2025). Injury to a peripheral nerve. "Following peripheral nerve injury, SRSCs function as stimulus receptors, receiving external stimuli and transmitting signals to typical repair SCs via the SPP1 signaling network." (PMID 40417312, 2025). "In summary, our data suggested that SPP1 and PKCα were significantly upregulated after peripheral nerve injury in clinical specimens." (PMID 32843960, 2020).
Pleural effusion (3 papers, 2014 to 2020). The presence of an excessive amount of fluid in the pleural cavity. "In this study, we have shown that SPP1 in pleural effusion has diagnostic characteristics for MPE similar to those of CEA in pleural fluid." (PMID 24758329, 2014). "In summary, our study suggests that quantitative determination of SPP1 concentrations in pleural effusions may provide an auxiliary diagnostic modality for differentiating between benign and malignant pleural effusion." (PMID 24758329, 2014). "In this study, the concentration of SPP1 in pleural effusion samples from 109 patients was determined by ELISA." (PMID 24758329, 2014). "Based on the cutoff value, the higher the SPP1 levels in pleural effusion specimens were, the lower the false diagnosis rate of MPE would be." (PMID 24758329, 2014). "SPP1 in pleural effusion can be used for the auxiliary diagnosis of MPE and used to determine the prognosis of patients with NSCLC." (PMID 24758329, 2014). "SPP1 expression was detected in all 109 pleural effusion specimens." (PMID 24758329, 2014). "Our results are in consistent with these previous studies; however, those studies did not analyze the association between SPP1 level and different clinical features, they and investigated samples of tumor tissue or blood instead of pleural effusion." (PMID 24758329, 2014). "The high-SPP1-expressing patients had a significantly greater number of extrapulmonary metastases than the low-expressing patients (P = 0.03), suggesting that SPP1 levels in the pleural effusion of NSCLC patients were positively correlated with the number of extrapulmonary metastases." (PMID 24758329, 2014). "The cut-off value was 1247.90 ng/ml (sensitivity 40.3%; specificity 95.8%; area under the curve (AUC) 0.660; 95% confidence interval (CI): 0.550-0.770), indicating that the SPP1 concentration in pleural effusion may have a role in the auxiliary diagnosis of MPE." (PMID 24758329, 2014). "SPP1 in MPE was an independent prognostic factor of NSCLC-induced MPE, indicating that SPP1 in pleural effusion can be used for the auxiliary diagnosis of NSCLC-induced MPE, and it may be a prognostic indicator for patient survival and risk of extrapulmonary metastases." (PMID 24758329, 2014).
polyp (3 papers, 2017 to 2024). A usually exophytic mass attached to the underlying tissue by a broad base or a thin stalk. "IL6 and SPP1 transcripts were only detected in nine and eight cancer samples, respectively, and were nearly absent in polyp patients and controls, suggesting that transcript levels were generally lower and more cancer-specific, or that these RT-PCR assays were less efficient." (PMID 39523395, 2024).
prostatic intraepithelial neoplasia (3 papers, 2023 to 2025). "Another study found that SPP1, produced by macrophages in the tumor environment, stimulates the growth of prostatic intraepithelial neoplasia (PIN) cells via the AKT and JNK pathways." (PMID 41391064, 2025). "In another study, M2 macrophage cytokine SPP1 accelerated the growth of prostatic intraepithelial neoplasia (PIN) when co-cultured on 3D Matrigel scaffolds." (PMID 36744644, 2023).
schistosomiasis (3 papers, 2016 to 2024). An infectious disease caused by parasitic trematodes of the genus Schistosoma that colonize human blood vessels and release eggs that can cause granulomatous reactions leading to acute (swimmer's itch or acute schistosomiasis syndrome) or chronic disease. "SPP1 is an important drug target for controlling hepatic pathological damage in schistosomiasis." (PMID 39590301, 2024).
schwannoma (3 papers, 2013 to 2025). A benign, usually encapsulated slow growing tumor composed of Schwann cells. "Other notable ECM-related genes include that we identified in our analysis with less evidence in schwannoma included: ITGA1, POSTN, SPP1, ID3, ADAMTS6." (PMID 40585242, 2025). "We found that upregulated genes PIK3CG, CSF1R, SPP1, and CCND1 and downregulated genes EGFR and VWF were significantly enriched in PI3K-Akt signaling pathway involved in VSs development, which can increase schwannoma cell proliferation, survival, and cell-matrix adhesion acting." (PMID 32733557, 2020).
synovitis (3 papers, 2021 to 2024). Inflammation of a synovial membrane. "In the present study, clodronate administration greatly suppressed synovitis, possibly through a reduction in Spp1 and Nampt expression in macrophages." (PMID 39563425, 2024).
tendinopathy (3 papers, 2019 to 2023). "Compared to the negative control group, overexpressing miR-337-3p significantly reduced the expression of chondro-osteogenic markers Spp1 and Col2a1 in patellar tendon of tendinopathy model." (PMID 31065679, 2020). "From the study, we believe that blocking the CD44 receptor on diseased tenocytes or knocking down the SPP1 gene in macrophages in the pathological environment may delay the occurrence and development of tendon HO, thus achieving a therapeutic effect on tendinopathy." (PMID 37280595, 2023).
thyroid (3 papers, 2020 to 2025). "Integration with conventional DEG signatures revealed a functionally cohesive module, with C1QA/B/C, FLT1, TEK, PDGFRB, SPP1, and HLA-DPB1 emerging as central regulators of thyroid irAEs." (PMID 41221294, 2025).
Ureteral obstruction (3 papers, 2022 to 2024). Obstruction of the flow of urine through the ureter. "Prior studies have shown the causal role of SPP1 in kidney disease in the unilateral ureteral obstruction (UUO), diabetic, and LPS-induced kidney disease models." (PMID 37906287, 2024).
age (2 papers, 2020 to 2026). A temporal measurement of the time period elapsed since an identifiable point in the life cycle of an organism. "This study highlighted the crucial role of MG Spp1 in preserving cognitive health and it could serve as the target for combating age‐related memory decline." (PMID 41549460, 2026).
airway hyperresponsiveness (2 papers, 2020 to 2025). "Recombinant SPP1 (rSPP1) administration increases IL-13 and MMP-9 in the lungs of SPP1−/− mice and exacerbates airway hyperresponsiveness." (PMID 40559389, 2025). "Airway hyperresponsiveness (AHR), bronchoalveolar lavage fluid (BALF), cell counts, histology, and Spp1 expression were assessed." (PMID 32009132, 2020).
ampullary cancer (2 papers, 2011 to 2019). "SPP1 expression is 27-fold higher in sporadic ampullary cancer compared to normal duodenum and serum OPN progressively increases from healthy controls to patients with ampullary adenoma to patients with sporadic ampullary cancer." (PMID 31211760, 2019).
asbestosis (2 papers, 2021 to 2025). A lung disorder caused by inhalation of asbestos fibers. "For instance, osteopontin (secreted phosphoprotein 1; Spp1) has been associated with the regulation of inflammation and mucin production in a murine model of asbestosis." (PMID 34200147, 2021). "In an animal model of asbestosis, SPP1 expression is elevated in bronchiolar epithelial cells, and Spp1−/− mice exhibit reduced inflammation and collagen gene expression." (PMID 40559389, 2025).
basal cell carcinoma (2 papers, 2021 to 2024). A carcinoma involving the basal cells. "To validate if C1QC+ TAMs and SPP1+ TAMs gene signatures can work better than M1 and M2 signatures in other cancers, we also analyzed another single cell data of advanced basal cell carcinoma (BCC)." (PMID 34295336, 2021).
biliary atresia (2 papers, 2021 to 2024). A rare, biliary tract disease characterized by progressive obliterative cholangiopathy of the intra- and extrahepatic bile ducts, occurring in the embryonic/ perinatal period, leading to severe and persistent neonatal jaundice and acholic stool. "For example, SPP1, TGFB1, JAG1, STAT1, and VIM were linked to congenital biliary atresia, and were confirmed to be strongly expressed in the endothelial and megakaryocyte." (PMID 34095116, 2021). "In addition, immune correlation analysis revealed that SPP1 expression was higher in resting CD4 memory T cells and lower in regulatory T cells in the diagnosis of biliary atresia, suggesting that SPP1 mediated CD4+ T-cell and regulatory T-cell infiltration." (PMID 38919629, 2024).
Candida infection (2 papers, 2017 to 2025). "In a mouse model of Candida infection, Spp1 deficiency completely ameliorated disease lethality." (PMID 40704794, 2025).
cataract (2 papers, 2009 to 2024). Partial or complete opacity of the crystalline lens of one or both eyes that decreases visual acuity and eventually results in blindness. "On the other hand, genes which are highly up-regulated in Dbl-lenses, such as Mmp12, Ccl2, and Spp1, have not been described in EMT occurring in these cataracts." (PMID 19759912, 2009).
chordoma (2 papers, 2024). Chordomas are rare malignant tumors arising from embryonic remnants of the notochord in axial skeleton. "GMFG secreted by ERS‐CAF reshapes the immune microenvironment possibly via recruiting SPP1+ macrophages to promote chordoma progression by binding to ITGB1 on tumor cells." (PMID 39207055, 2024). "Collectively, these data suggest that ITGB1 on tumor cells might likely expedite chordoma progression by inducing an inhibitory immune microenvironment through recruiting SPP1+ TAMs, although the precise molecular mechanisms deserve further exploration." (PMID 39207055, 2024). "Collectively, the findings suggest that ERS‐CAF regulates SPP1+ macrophage to aggravate chordoma progression via the IER2/GMFG/ITGB1 axis, which may be targeted therapeutically in future." (PMID 39207055, 2024).
chronic lung disease (2 papers, 2025). According to the definitions of the American and British Thoracic Societies, including pulmonary functional tests, X-rays, and CT scans for items such as fibrosis, bronchiectasis, bullae, emphysema, nodular or lymphomatous abnormalities. "In summary, SPP1 constitutes a common core pathogenic mechanism of various chronic lung diseases by driving ECM remodeling, EMT and immune inflammation regulation." (PMID 41293726, 2025). "Moreover, the isoform-specific effects of SPP1 and its post-translational modifications in acute and chronic lung diseases remain largely unexplored." (PMID 40559389, 2025).
duodenal cancer (2 papers, 2019 to 2023). "Among the DEGs identified, SPP1 and CEACAM5 have potential as serum biomarkers for duodenal cancer in FAP." (PMID 31211760, 2019).
dysplasia (2 papers, 2007 to 2015). A usually neoplastic transformation of the cell, associated with altered architectural tissue patterns. "We validated OPN/SPP1 overexpression in an independent cohort of 107 EAC samples using real-time RT-PCR and found significantly higher expression of OPN/SPP1 in all stages of EAC compared with Barrett's metaplasia (BE) and dysplasia (p < 0.01 for stage I EAC and p < 0.0001 for all other stages)." (PMID 26068949, 2015).
dystrophin deficiency (2 papers, 2019 to 2020). "OPN, encoded by SPP1, acts as a pro-inflammatory cytokine in muscle, and high OPN expression worsen the phenotype of dystrophin deficiency." (PMID 32849198, 2020).
essential thrombocytemia (2 papers, 2020 to 2023). "Ruberti found that SPP1 plasma levels are significantly higher in Primary myelofibrosis compared with essential thrombocytemia and polycytemia vera patients." (PMID 32778054, 2020).
follicular thyroid cancer (2 papers, 2019 to 2021). "The SPP1 gene expression was not changed by VIB and hyper-g in ML1 follicular thyroid cancer cells." (PMID 31731625, 2019).
hip fracture (2 papers, 2020 to 2025). Traumatic or pathological injury to the hip in which the continuity of either the femoral head, femoral neck, intertrochanteric or subtrochanteric regions is broken. "The acute phase protein PTX3 showed similar associations as those for SPP1, with higher hip fracture risk, lower BMD, higher bone turnover, and lower fat and lean mass." (PMID 39919333, 2025).
HIV-associated neurocognitive disorder (2 papers, 2015 to 2020). HIV-associated neurocognitive disorder (HAND) remains a common complication of HIV infection in the combination antiretroviral therapy (ART) era. "Previous in vitro, ex vivo, and rhesus macaque studies have implicated a role for the multifunctional protein osteopontin (OPN) or secreted phosphoprotein-1 (SPP1) in proinflammatory signaling in HIV-associated neurocognitive disorders (HAND)." (PMID 32943056, 2020).
Hydrocephalus (2 papers, 2019 to 2025). Hydrocephalus is an active distension of the ventricular system of the brain resulting from inadequate passage of CSF from its point of production within the cerebral ventricles to its point of absorption into the systemic circulation. "Identifying the cellular source of the Spp1 gene in the AQP4−/−-NH/CD1 mouse was impossible, given the loss of the obstructive hydrocephalus phenotype." (PMID 41226330, 2025). "Future work will include verification of Spp1 expression and Cd11c+ microglia presence once a new colony expressing the hydrocephalus phenotype is available." (PMID 41226330, 2025). "In this scenario, Spp1 would be positioned as the key gene orchestrating the amelioration of congenital hydrocephalus because it is over-expressed only in animals AQP4−/−-NH that did not develop hydrocephalus." (PMID 41226330, 2025). "In light of these observations, it is conceivable that changes in Spp1 expression associated with AQP4 deficiency could affect the normal development of the aqueduct and contribute to the onset of hydrocephalus." (PMID 41226330, 2025). "In summary, our findings suggest that the development of obstructive hydrocephalus in a small proportion of AQP4−/−/CD1 mice may be associated with a reduced presence of CD11c+ microglia and lower Spp1 (osteopontin) expression near the aqueduct of Sylvius during early postnatal development." (PMID 41226330, 2025). "Conversely, lack of Spp1 gene during the first postnatal days (P0-P11) would be a critical condition that primes the brain for the development of hydrocephalus in the absence of AQP4." (PMID 41226330, 2025).
immune deficiencies (2 papers, 2018 to 2024). "Numerous genes have been implicated in the pathogenesis of SLE, particularly components of the interferon pathways such as IRF5, STAT4, and SPP1, which likely reflect intrinsic immune deficiencies in SLE patients." (PMID 39194726, 2024).
intervertebral disc degeneration (2 papers, 2025). "In conclusion, SPP1 activates ITGα5/β1 to inhibit mitophagy, accelerates NPs degeneration, and induces calcification, thereby leading to intervertebral disc degeneration (IVDD) and calcification, identifying the potentially unknown mechanism and relationship between IVDD and calcification." (PMID 39721032, 2025). "This study elucidated the function and regulatory mechanisms of SPP1‐ITGα5/β1 in IVDD by inhibiting mitophagy and proposed a potential therapeutic approach for strategy for intervertebral disc degeneration and calcification." (PMID 39721032, 2025). "In nucleus pulposus cells, secreted phosphoprotein 1 (SPP1) impeded PINK1/Parkin-mediated mitophagy via the integrin α5β1 pathway, accelerating cellular senescence and intervertebral disc degeneration." (PMID 40814109, 2025).
juvenile idiopathic arthritis (2 papers, 2011 to 2023). Juvenile idiopathic arthritis (JIA) is the term used to describe a group of inflammatory articular disorders of unknown cause that begin before the age of 16 and last over 6 weeks. "Conversely, there are investigations that associate SPP1 SNP with RA susceptibility, joint destruction, the course of oligoarticular onset juvenile idiopathic arthritis (JIA), and the positivity to anti-citrullinated protein antibodies (ACPA)." (PMID 36979437, 2023).
kidney injury (2 papers, 2019 to 2023). Trauma to the kidney. "We found that the protein SPP1, C3 and HAVCR1 might also play critical roles in the ER stress and phagocytosis in the CaOx crystal formation process and its related kidney injury." (PMID 36932340, 2023).
lymphopenia (2 papers, 2021 to 2022). Reduction in the number of lymphocytes. "Coarse-grained clustering allowed us to detect a severity associated neutrophilia and lymphopenia, but also a SPP1+ macrophage population associated with severe patients’ survival." (PMID 33674591, 2021).
nephritis (2 papers, 2019 to 2026). Inflammation of renal tissue. "Single-cell RNA sequencing identified a distinct monocyte-derived Anxa1+Spp1+ macrophage subset that expands during nephritis and displays a profibrotic transcriptional signature." (PMID 41800263, 2026).